TXNIP (thioredoxin interacting protein)
Diseases named in the same sentence as TXNIP in open-access papers (continued):
Sharing a sentence is not in itself a finding about the gene and the disease.
tumor (continued). "TXNIP is a member of the α-arrestin family and acts as a tumor suppressor." (PMID 31208077, 2019). "Moreover, miR-411-5p/3p expression was significantly upregulated, and SPRY4 and TXNIP protein expression was downregulated in tumor tissues of the pLenti-miR-411 group." (PMID 30390072, 2019). "In view of its tumor suppressor role, we postulate that enhanced TXNIP expression in LS might be responsible for tumor protection in this condition." (PMID 31208077, 2019). "Therefore, a better understanding of TXNIP’s context-dependent roles would shed light on its importance to calcitriol’s effects in tumor cells." (PMID 29534438, 2018). "Moreover, TXNIP expression in tumor samples from patients with primary HCC reveals that TXNIP levels are elevated in HCC tissues compared to normal liver tissues and adjacent non-tumor tissues." (PMID 30627326, 2018). "Therefore, compounds that reactivate TXNIP expression are viewed as promising anti-tumor candidates, such as the histone deacetylase inhibitor suberoylanilide hydroxamic acid and the histone methyltransferase inhibitor 3-Deazaneplanocin A." (PMID 29534438, 2018). "Molecular analysis of the TXNIP tumor‐suppressive effect could lead to an understanding of the mechanisms of tumor progression or to development of novel cancer therapies." (PMID 30410860, 2018). "Moreover, a large body of evidence supports the role of TXNIP as a tumor suppressor in several cancer types." (PMID 30627326, 2018). "Extensive evidence shows that TXNIP acts as a tumor suppressor." (PMID 28035074, 2017). "Some of the up-regulated genes act as tumor suppressors (TXNIP, EGR1, and PPP1R15A)." (PMID 28035074, 2017). "In addition, we identified two novel target genes of miR-204/211, MX1 and TXNIP, which are tumor suppressors." (PMID 27121770, 2016). "Given previous evidence of TXNIP as a tumor suppressor and mediator of ROS responses, we tested the hypothesis that the effect of pterostilbene might be dependent on TXNIP activation and/or induction of reactive oxygen species (ROS)." (PMID 27689322, 2016). "Therefore, downregulation of TXNIP in a tumor has the potential to promote cell survival, growth, invasion, and metastasis." (PMID 24645981, 2014). "It is possible that if our study had been temporally extended, the trend in tumor volume attenuation in the TXNIP-overexpressing group might have reached statistical significance." (PMID 24645981, 2014). "TXNIP has been shown to be a tumor suppressor in other animal models of cancer as well." (PMID 24645981, 2014). "In addition to inducing a metabolic shift important to tumor biology, downregulation of TXNIP has other important effects in cancer cells that contribute to tumor promotion and/or progression." (PMID 24645981, 2014). "In addition, the strong reduction in TXNIP protein expression in various types of tumors suggests that this protein functions as a tumor suppressor." (PMID 24098117, 2013). "TXNIP is a negative regulator of cellular oxidative tolerance by binding thioredoxin and as a feedback regulator of S-nitrosylation relevant in the cellular adaptive response to tumor microenvironmental stresses." (PMID 20844768, 2010). "Furthermore, when compared to the oe-NCL + oe-MYC + oe-NC group, the oe-NCL + oe-MYC + oe-TXNIP group exhibited enhanced tumor cell proliferation, reduced apoptosis, significantly decreased permeability, and a notable increase in the invasive spread capacity of spheroids." (PMID 40346484, 2025). "For instance, TXNIP amplification may hyperactivate redox-sensitive senescence checkpoints, while SREBF1 loss could disrupt lipid homeostasis, creating a permissive niche for tumor survival." (PMID 40299498, 2025). "Tumor effector memory CD8 T cells demonstrated overexpression of CCR7, IL7R, and CXCR4, which are associated with a naïve-like T cell state and inversely associated with T cell polarization and effector T cell function, as well as TXNIP, which negatively regulates T cell proliferation." (PMID 40848148, 2025).
tumor (continued). "Strong expression of TXN and TXNIP in cytoplasm, at cell membrane and translocation into nuclei of EVT cells, associated precursor lesions as well as in ESRD/ACRD associated tumours suggest as the involvement of TXNIP/TXN signalling in the development of these unique type of tumours." (PMID 39020292, 2024). "Furthermore, we examined the effect of TXNIP knockdown on the malignantpotential of tumor cells." (PMID 38229544, 2024). "However, it must be considered that additional tumor suppressor activities have been described for TXNIP that may also contribute to Dpep-promoted cancer cell death, including promotion of cell cycle arrest, inflammation and tumor immune responses." (PMID 38920655, 2024). "In addition to tumor-specific functions, TXNIP may also exert opposite functions at different stages during cancer progression." (PMID 37794178, 2023). "Thus, TXNIP is a potent tumor suppressor in BCR-ABL-induced CML." (PMID 37095099, 2023). "Notably, TXNIP acts as a tumor suppressor and is often downregulated in cancer cells." (PMID 36860653, 2023). "In addition, TXNIP has gained significant attention due to its wide range of functions in energy metabolism, insulin sensitivity, improved insulin secretion, and also in the regulation of glucose and tumor suppressor activities in various cancers." (PMID 33803178, 2021). "Similarly, a synergistic action with the tumor drug paclitaxel on A549 cells was exerted by activation of the ASK1/p38 MAPK signaling pathway and, consequently, of the thioredoxin-interacting protein (TXNIP)-associated NLRP3 inflammasome (TXNIP-NLRP3)." (PMID 33435246, 2021). "Moreover, the miR-135b-5p/TXNIP axis also contributes to the anti-tumor effect of cisplatin in EC." (PMID 34277424, 2021). "Thus, TXNIP might display immune activation in a tumor site and may aid in predicting response to modern immune therapy." (PMID 33081035, 2020). "Hence TXNIP expression might be used to monitor the functional state of tumor-infiltrating leukocytes in tissue sections." (PMID 33081035, 2020). "However, similar to the data analyzed from TCGA, low levels of TXNIP in the primary tumor correlated to worse overall survival in the TMA cohort of 22 patients with stage 1 and 2 disease (p = 0.2) although the results do not reach statistical significance due to a small sample size." (PMID 30479697, 2018). "Finally, we examined the effect of TXNIP overexpression in an in vivo orthotopic tumor model." (PMID 24645981, 2014). "We next investigated whether TXNIP was differentially expressed at the tumor tissue level." (PMID 24645981, 2014). "In addition, transcriptional activation of the FOXO target gene TXNIP acts as a tumor suppressor." (PMID 24112473, 2013). "To further investigate the relationship between Trx system and tumor immunity, we obtained the mRNA expression level of TXN, TXNRD1 and TXNIP at single-cell level using 10 datasets from TISCH data." (PMID 39744566, 2025). "What is more, miR-411-5p also reduces molecular levels of thioredoxin interacting protein (TXNIP), a tumor suppressor that regulates cell cycle progression." (PMID 40332376, 2025). "We evaluated the stromal and immune cells in tumor tissues using the ESTIMATE method, and found that stromal and immune scores were lower in the high TXN, high TXNRD1, and low TXNIP groups in most tumor species." (PMID 39744566, 2025). "Consistent with the initial inhibitory events, knocking down CAST in TXNIP-OE HCC-1954 cells led to a significant reduction in cell proliferation, colony formation, and tumor growth in a mouse xenograft model." (PMID 40175348, 2025). "We next investigated the implication of TXNIP in modulating immune effector functions in primary human T cells and showed that TXNIP depletion increased IFN-γ secretion and tumor cell killing." (PMID 40260243, 2025).
tumor (continued). "We performed RNA sequencing of COR-treated HCC cells to investigate the mechanism by which COR induces tumor cell death and determined that ERS and expression of TXNIP was significantly upregulated in cells cultured with COR." (PMID 40008893, 2025). "In this study, we demonstrate that the BET inhibitor JQ1 induces the upregulation of Thioredoxin Interacting Protein (TXNIP), which mediates the anti-tumor effects of JQ1." (PMID 41249136, 2025). "TXNIP, as well as TXN and TXNRD1 have been demonstrated in several studies to regulate tumor immunity, especially T-cell function and differentiation." (PMID 39744566, 2025). "Here, we demonstrate that TXNIP stability is negatively regulated by WWP1 in AML cells, a tumor in which additional therapeutic targets are needed." (PMID 39364720, 2025). "This was accompanied by significantly upregulated expression levels of thioredoxin-interacting protein (TXNIP), a gene that has been reported to be a tumour and metastasis suppressor." (PMID 39199548, 2024). "We confirmed the expression of TXNIP in a patient CRCLM sample, in tumor regions where immune cells cluster (dashed squares)." (PMID 38358352, 2024). "Strong TXNIP expression was seen in epithelial cells, myo-fibroblasts and endothelial cells and weak TXN expression in ESRD/ACRD kidneys and tumours." (PMID 39020292, 2024). "This study aimed to determine of TXNIP and TXN expression and their cellular localisation in ESRD/ACRD kidneys, tumour precursor lesions and tumours by immunohistochemistry." (PMID 39020292, 2024). "MIF is also able to induce NF-κB activation through its interaction with thioredoxin-interacting protein (TXNIP), a tumor suppressor and known inhibitor of NF-κB activity." (PMID 38145300, 2024). "A study conducted with BC cell lines and tissue samples identified tumor suppressors MX1 and TXNIP as targets of miR-204, suggesting that the functions of this miRNA are directed toward cell death suppression and proliferation stimulation." (PMID 39199587, 2024). "In the case of BC, the tumor suppressors MX1 and TXNIP have been identified as direct targets of miR-204." (PMID 39199587, 2024). "Surprisingly, multiple previously reported tumor suppressors of KIRC were found in these downregulated genes, including SOX6, DAPK1, PDZK1, TXNIP, DAB2IP, and CMTM4." (PMID 37737260, 2023). "Its expression is increased by stressors commonly found in neoplastic cells and the wider tumor microenvironment (TME), and, as such, TXNIP has been extensively studied in cancers." (PMID 37794178, 2023). "In the tumor tissue, DEX treatment significantly reduced the expression of CTP1A and TXNIP, which are involved in reactive oxygen species (ROS)-related regulatory mechanisms associated with NLRP3 inflammasome activation." (PMID 37528154, 2023). "Some studies have revealed that thioredoxin-interacting protein (TXNIP) is a thioredoxin-binding protein that can inhibit cell proliferation and induce apoptosis, acting as a tumor suppressor in some cancers." (PMID 36091786, 2022). "One mechanism is via suppressing thioredoxin-interacting protein (TXNIP), which is a tumor suppressor that regulates glucose flux." (PMID 36712976, 2022). "In addition, the study has also demonstrated that NaBu-induced TXNIP also interacts with TNF receptor-related factor 6 (TRAF6) through its PPxY motif, thereby causing the change of TXNIP expression and its ubiquitination and affecting the migration and proliferation of the tumor cells in NSCLC." (PMID 35450411, 2022). "The thioredoxin system is an essential factor in the anti-tumor responses of CD8+ T cells and is under inhibitory control of the negative regulator thioredoxin-interacting protein (TXNIP), which is down-regulated upon T cell stimulation." (PMID 35008532, 2021). "Among those, SLC2A12, TXNIP, and MAFG were found to have low expressions in the tumor tissue samples, while the others were highly expressed." (PMID 34386423, 2021).
tumor (continued). "TXNIP expression and elevated level of ROS is required for VEGF-mediated VEGFR2 activation and proliferation of endothelial cells during tumor angiogenesis." (PMID 34433833, 2021). "As the disease progresses, miR-106b can regulate the expression of the tumor suppressor genes p21 and thioredoxin-interacting protein (TXNIP) and promote the proliferation of tumor cells in MF." (PMID 34966672, 2021). "Protein expression analyses of the tumor relevant genes CREM GLS2, PER3 and TXNIP mostly showed a diametrical regulation compared to mRNA expression in both cell lines under acidotic conditions." (PMID 33407762, 2021). "Finally, we investigated whether miR-135b-5p/TXNIP axis is engaged in the anti-tumor effect of DDP." (PMID 34277424, 2021). "It has, however, been shown that miR-373 decreases the expression of TXNIP by interacting with the 3′ untranslated region (UTR) of TXNIP to reduce TXNIP-dependent ROS, activate EMT, and thereby promote tumor migration and invasion." (PMID 33194655, 2020). "Researchers have shown that the resulting high levels of glucose promote TXNIP expression by activating the p38 MAPK and ERK pathways, thereby promoting tumor development." (PMID 33194655, 2020). "Thioredoxin interacting protein (TXNIP) is a metabolic protein critically involved in redox homeostasis and has been proposed as a tumor suppressor gene in a variety of malignancies." (PMID 33081035, 2020). "Furthermore, we elucidated the action mechanisms of ETS1 as a tumor suppressor not only by directly activating down-stream targets linked with tumor cell proliferation/growth but also trans-activation of other tumor suppressor genes, such as ADAMTS9, TXNIP, STAT5A, and NOTCH1." (PMID 32477936, 2020). "In this study, we demonstrated that the up-regulation of TXNIP is, at least partially, responsible for the JQ1-induced cell death, which further supports the role of TXNIP as a tumor suppressor." (PMID 29996811, 2018). "Neural lineage markers, such as NCAM1 (early) and NPTX1 (neuronal), were highly expressed in 143BNSC tumours, whereas genes involved in cancer proliferation, including EYA2, VCAN, HMGA1 and TXNIP, were highly expressed in 143BGBM tumours." (PMID 27551510, 2016). "B6H12-treated bCSCs showed an up-regulation of thioredoxin-interacting protein (TXNIP) and LOX (lysyl oxidase), which are known tumor suppressors." (PMID 26840086, 2016). "Thioredoxin-interacting protein (TXNIP) has multiple functions, including tumor suppression and involvement in cell proliferation and apoptosis." (PMID 24098117, 2013). "For example, TXNIP (thioredoxin-interacting protein), EGR1, CBX7, HOXA9 and FOXN3 (checkpoint repressor 1) have tumor suppressor functions and are targeted by the potentially oncogenic miRNA miR-93, miR-183, miR-181b, miR-182 and miR-7." (PMID 21375733, 2011). "Moreover, TXNIP gene expression level was higher in CD4+ T cells originating from blood compared to adjacent normal tissue, and even more compared to tumor samples." (PMID 40260243, 2025). "Given CAST’s role as a tumor promoter, the elevated CAST levels in TXNIP-OE HCC-1954 cells may counteract TXNIP’s antitumor effects." (PMID 40175348, 2025). "Second, the unexpected acceleration in tumor growth observed in TXNIP-overexpressing HCC-1954 cells after four weeks suggests that additional, unknown mechanism(s) may influence TXNIP’s anticancer effects." (PMID 40175348, 2025). "Additionally, the ERS-pyroptosis axis is closely associated with metabolic reprogramming, such as glucose metabolism disorders and TXNIP/NLRP3 pathway activation, influencing tumor progression." (PMID 41407677, 2025). "In contrast, TXNIP overexpression reduced HCC-1954 tumor growth for up to 33 days following cell injection, followed by a late acceleration in tumor growth due to an unknown mechanism(s)." (PMID 40175348, 2025).
tumor (continued). "Our data showed for the first time in primary human T cells that deletion of TXNIP led to increased IFN-γ production and expression of T cell activation markers (i.e. CTLA-4 and CD25) and could result in greater tumor cell killing in vitro." (PMID 40260243, 2025). "Together, these results could also partly explain the tumor-promoting function of CAST, which was upregulated in TXNIP-OE HCC-1954 cells, by counteracting the tumor suppressor activity of TXNIP." (PMID 40175348, 2025). "In this study, we explored the mechanism underlying TXNIP’s tumor suppression activities using two ER/PR negative BC models - MDA-MB-231 (TNBC; high TXNIP expression) and HCC-1954 (HER2-positive; low TXNIP expression)." (PMID 40175348, 2025). "It remains unclear whether enhanced calpain kinase activity contributed directly to reduced CAST-KD_TXNIP-OE HCC-1954 cell proliferation and tumor growth." (PMID 40175348, 2025). "To understand whether TXNIP mediated the anti-tumor effects of JQ1, we knocked out TXNIP in HepG2 cells with two sgRNA and subsequently assessed the sensitivity of these cells to JQ1." (PMID 41249136, 2025). "Since CAST has tumor-promoting activity, we hypothesized that CAST upregulation in TXNIP-OE HCC-1954 cells might explain the late-onset acceleration in the growth of TXNIP-OE HCC-1954 tumors in NSG mice." (PMID 40175348, 2025). "It was already known that GLUT1 was internalized by TXNIP in clathrin-coated vesicles and that its subcellular location is important in tumor progression; however, its importance is not so well studied in the context of PCa-ADT." (PMID 41213907, 2025). "The expression of TXNIP was slightly greaterin adjacent noncancerous tissue than that in tumor tissue." (PMID 38229544, 2024). "While some studies suggest that it promotes cell death by regulating genes like FOXA1, Bcl-2, JAK2, and PTEN, others indicate that it might suppress cell death by targeting tumor suppressors like MX1 and TXNIP and influencing ERα signaling." (PMID 39199587, 2024). "TXNIP exhibited a different expression between drug-resistant and non-drug-resistant tumor cells, suggesting a potential role in drug resistance." (PMID 39061897, 2024). "Therefore, TXNIP upregulation attenuates the activity of TXN, leading to decreased proliferation and cell cycle progression in tumor cells." (PMID 37037466, 2023). "Thioredoxin-interacting protein (TXNIP) is a metabolism-related protein that plays a tumor suppressor role in various malignant tumors; however, the specific role of TXNIP in tumor chemoresistance has not been reported." (PMID 35414060, 2022). "Moreover, after the drug combination treatment, we found that TXNIP, Bax, and γ-H2AX expressions were upregulated while the bcl-2 and Ki67 expressions were downregulated in the tumor sections of nude mice." (PMID 35414060, 2022). "To establish the role of TXNIP and downstream genes HIF1α and IL1β in the biology of cRCC, we have applied immunohistochemistry to tissue multi-arrays containing tumours of patients without detectable metastases at the time of operation." (PMID 34433833, 2021). "One group of 512 tumours (74%) without cytoplasmic expression of TXNIP, and the other group displaying medium or strong cytoplasmic TXNIP staining in 95 (14%) and 84 (12%) cases, respectively." (PMID 34433833, 2021). "Even though TXNIP is reported to be a tumor suppressor, TXNIP reduction mediated by DASA-58 treatment does not hamper the antitumor effects of other chemotherapeutics." (PMID 33482908, 2021). "In highly differentiated cRCC resembling the classic “Grawitz” tumour a fine network of TXNIP positive endothel cells and tumour cells without TXNIP staining was seen." (PMID 34433833, 2021). "Interestingly, UHRF1 downregulation in RCC cell lines induced the upregulation of TXNIP expression and apoptosis, suggesting that UHRF1 inhibits the expression of TXNIP in RCC through epigenetic mechanisms, thereby promoting tumor progression." (PMID 33922029, 2021).